DMRTA2 (DMRT like family A2)
Description:
May be involved in sexual development.
Synonyms: DMRT5
Tractability: No criterion of Open Targets' tractability assessment is met for any kind of drug.
Gene: Protein-coding gene on chromosome 1 (50,417,550 to 50,423,468, reverse strand). Ensembl gene ENSG00000142700.
Subcellular location: Nucleus
Subcellular location (Human Protein Atlas): Mitochondria; Nucleoplasm
Gene Ontology:
Molecular function: sequence-specific double-stranded DNA binding; DNA-binding transcription factor activity, RNA polymerase II-specific; RNA polymerase II cis-regulatory region sequence-specific DNA binding; double-stranded DNA binding; identical protein binding; sequence-specific DNA binding
Biological process: regulation of transcription by RNA polymerase II; sex differentiation; regulation of DNA-templated transcription
Cellular component: chromatin; nucleus
Genetic constraint (gnomAD): Loss-of-function variants: 8 observed, 11.67 expected, observed/expected ratio (o/e) 0.69, 90% interval 0.4 to 1.24. The synonymous counts are far from expectation, so gnomAD's model fits this gene poorly and the ratio says little. Missense variants: 605 observed, 473.18 expected, observed/expected ratio (o/e) 1.28, 90% interval 1.2 to 1.37. Synonymous variants: 373 observed, 239.16 expected, observed/expected ratio (o/e) 1.56, 90% interval 1.43 to 1.7.
Homologues: Orthologues: chimpanzee DMRTA2 (99% identical), macaque DMRTA2 (98% identical), pig DMRTA2 (96% identical), rat Dmrta2 (94% identical), dog DMRTA2 (93% identical), mouse Dmrta2 (93% identical), rabbit DMRTA2 (89% identical), tropical clawed frog dmrta2 (59% identical), zebrafish dmrta2 (55% identical), Caenorhabditis elegans dmd-7 (13% identical), Caenorhabditis elegans dmd-9 (9% identical). Paralogues in human: DMRTA1 (36% identical), DMRT3 (24% identical), DMRT2 (18% identical), DMRT1 (18% identical), DMRTB1 (15% identical), DMRTC2 (15% identical), DMRTC1 (7% identical), DMRTC1B (7% identical).
Diseases named in the same sentence as DMRTA2 in open-access papers:
DMRTA2 is named in the same sentence as 8 diseases in open-access papers, as found by Europe PMC text mining. Sharing a sentence is not in itself a finding about the gene and the disease. The quoted sentences say what the papers report.
microcephaly (3 papers, 2020 to 2025). A congenital or acquired developmental disorder in which the circumference of the head is smaller than normal for the person's age and sex. "This phenotype in microcephaly appears to be consistent with cortical malformations in Dmrta2 KO mice." (PMID 34955736, 2021).
malignant glial tumors (2 papers, 2017 to 2024). "Among these genes, DMRTA2 encodes a transcription factor involved in human female germ cell development;21KCNG2 encodes a potassium channel subunit whose altered expression has been associated with malignant glial tumors;22 and PSMD10 encodes a regulatory subunit of the 26S proteasome." (PMID 27775072, 2017). "We conclude that DMRTA2 is a new player in gliomagenesis and tumor neovascularization and due to its high expression in malignant gliomas could be a biomarker and potential target for new therapeutic strategies in glioblastoma." (PMID 38509074, 2024).
embryonal carcinoma (1 paper, 2025). A non-seminomatous malignant germ cell tumor characterized by the presence of large germ cells with abundant cytoplasm resembling epithelial cells, geographic necrosis, high mitotic activity, and pseudoglandular and pseudopapillary structures formation. "To address the possibility that Dmrta2 affects Pax6 E60 enhancer activity and investigate its mechanism of action, we performed transfection experiments in P19 mouse pluripotent embryonal carcinoma cells that have neurogenic potential." (PMID 40541527, 2025).
cancer (1 paper, 2022). A tumor composed of atypical neoplastic, often pleomorphic cells that invade other tissues. "DMRTA2 has been found to regulate the expression of Hes1 gene, and this gene has been studied to have roles in cancer stem cell (CSC) maintenance, metastasis, and drug-induced apoptosis antagonism." (PMID 34976314, 2022).
DMRTA2 also shares sentences with these, for which no sentence is quoted: atherosclerosis (1 paper); glioblastoma (1); glioma (1); tumor (1).